ERBB2 (erb-b2 receptor tyrosine kinase 2)
Diseases named in the same sentence as ERBB2 in open-access papers (continued):
Sharing a sentence is not in itself a finding about the gene and the disease.
tumor (continued). "The trastuzumab moiety of T-DM1 binds ErbB2 on the tumor cell surface (this likely does not require ErbB2 to be active), T-DM1 is internalized by the cells, trastuzumab is degraded, and DM1 kills the cells." (PMID 33023655, 2020). "Age, larger tumor size, and ERBB2 positivity demonstrated nonsignificant trends toward poor chemotherapy outcomes." (PMID 32644137, 2020). "IHC staining confirmed ERBB2 target molecule expression on small tumor lesions but not on established tumors in the liver, probably due to the autofluorescence of the liver tissue and bile." (PMID 33193388, 2020). "Her ERBB2-overexpressing tumor did not however present a somatic second hit affecting PALB2, nor have a high HRD score." (PMID 32295625, 2020). "None of the cell lines overexpressed HER2 transcripts (ERBB2), consistent with the original tumor diagnosis." (PMID 32576280, 2020). "For example, tumours but not metastasis were observed in BALB/c mice whose mammary fat pad was injected with HC11 cells transformed in vitro by oncogenic NeuT/ErbB2." (PMID 33297592, 2020). "In the tumor group showing PIWIL3 emerging expression, significant positive associations were observed with PR- status (p = 0.026), ERBB2-negative status (p = 0.0004) and molecular subtype (p = 0.0017)." (PMID 33008024, 2020). "Tumour #1 had low-level ERBB2 amplification; however, tumour #2 showed no ERBB2 amplification on HER2 SISH during the study." (PMID 31929516, 2020). "Through use of HER2-CAR-NK cells, and direct injection into the tumor site, ErbB2-NK-92/5.28z CAR-NK will maintain effector function despite the potential antigen loss, which would return cytotoxic function of adoptively transferred cells to that of baseline NK cells." (PMID 32751977, 2020). "CAR CIK cells efficiently and selectively lysed ERBB2-positive tumor cells, which only showed minimal sensitivity to WT CIK cells, whereas parental ERBB2-negative tumor cells remained unaffected." (PMID 33193388, 2020). "According to the blood CEA values and CT scan, the tumor acquired resistance to anti-EGFR treatment within 9 months and plasma-Seq revealed a novel focal amplification on 17q12, including ERBB2, which represents an established mechanism of resistance to anti-EGFR therapy." (PMID 32087735, 2020). "Levels of ERBB2 copy number, TCL, and TMB were positively correlated with the tumor biomarker CEA." (PMID 33377634, 2020). "This includes disease stage, histologic type, histologic grade, tumor size, and the expression or lack thereof of two steroid receptors [estrogen (ER) and progesterone (PgR)] and the human epidermal growth factor receptor-2 (HER2/ErbB2)." (PMID 35582612, 2020). "Lentiviral vectors have been broadly used to generate NK cells expressing CARs with 1st, 2nd and 3rd generation designs which target different tumor antigens including CD19, CD20, TF in TNBC, CD33, CD7, CD22, ErbB2, EpCAM, Glypian-3 (GPC3), CS1, EGFR, B cell maturation antigen (BCMA) and CD4." (PMID 32707982, 2020). "In total, our findings using orthogonal sequencing and immunohistochemistry validate further the ability of our cfDNA assay to identify ERBB2 CNVs in BC without prior knowledge of tumour sequencing." (PMID 33033274, 2020). "In the tumor group showing PIWIL2 underexpression, significant positive associations were observed with PR- status (p = 0.0025), ERBB2 negative status (p = 0.039) and molecular subtype (p = 0.004)." (PMID 33008024, 2020). "Although it remains speculative, patients with CNV in ERBB2 and CNV in TOP2A in the primary tumor and/or lymph node metastasis may benefit from HER2- or TOP2A-targeted therapy." (PMID 33298978, 2020).
tumor (continued). "Apart from confirming targets, such as ERBB2 and S100A11, which are exclusively upregulated in the tumour epithelial cells, qPCR data confirmed that stromal targets such as SPARC, TIMP1, IGFBP7, COL1A1 were upregulated specifically in stromal components and not in epithelial components." (PMID 31959771, 2020). "Mice with delayed ERBB2-CAR CIK cell treatment on days +22 and +57 after tumor cell injection experienced significantly improved survival compared to untreated controls (p < 0.01), whereas WT CIK cell-treated mice only showed a trend toward improved survival (p > 0.07)." (PMID 33193388, 2020). "In the primary tumor, most CNV were found in MYC, CCND1, ERBB2 and CCNE1." (PMID 33298978, 2020). "For example, as previously noted by others, we detected ERBB2 expression in four patient BM samples, although the corresponding primary tumor was ERBB2 negative." (PMID 31432366, 2019). "The significantly high baseline ERBB2-GS in AI non-responders suggests tumours with high HER2 signalling activity even in HER2− tumours were predictive of poor response." (PMID 31892336, 2019). "One tumor harbored a duplication of ERBB2 and high expression of HER2 protein." (PMID 30499260, 2019). "As ERBB2+ BC cells heavily depend on ERBB2 receptor signaling for their growth and survival, and because CHD4 depletion inhibits BC tumor development in the MMTV/NeuT model, we hypothesized that CHD4 silencing might impair the ERBB2 signaling pathway." (PMID 30967373, 2019). "Herein it revealed that in contrast to this ErbB2-Herceptin line, the YS110 treatment abundantly induces nuclear localization of CD26 and in consequentially suppresses POLR2A expression, leading to inhibition of tumor cell growth." (PMID 31398954, 2019). "Since the parental anti-hHER2 antibody of [fam-] trastuzumab deruxtecan does not bind to mouse ERBB2, we prepared a mouse cell line that stably expresses the human target gene and used those cells to construct an immunocompetent mouse tumor model." (PMID 31574081, 2019). "Some of these changes were in line with RNAseq data, such as ERBB2/HER2 which was massively upregulated in both, the KRASWT tumor proteome (also compared to all of our reference proteomes) and transcriptome as a consequence of a gene amplification (region chr17:37, 690, 344-40,762,015)." (PMID 31805664, 2019). "On the other hand, ST8176AA1 but not trastuzumab induced significant acetylation of histones and alpha-tubulin in ErbB2+, but not in ErbB2- (data not shown), tumor cells of different origin." (PMID 32039017, 2019). "Trastuzumab changed the treatment paradigm of breast cancer but it did not solve the problem of tumor resistance that, in turn, promoted its use in combination with chemo or with the second anti-ErbB2 antibody pertuzumab." (PMID 32039017, 2019). "ERBB2 DNA and RNA (ICD and ECD) and TOP2α DNA and RNA status: (+ increased, = maintained and – decreased) considering the cut-off 2-fold and ERBB2 protein status following the 2013 ASCO/CAP guidelines (and maintained in the 2018 recommendations) of each of each tumor sample." (PMID 31301170, 2019). "However, after nicotine exposure, the luciferase activity in the tumor region was dramatically reduced to 26.3% (blue) of the original level, indicating that nicotine strongly dissociated CHRNA9/ERBB2 complex formation in this animal model." (PMID 31311925, 2019). "We noted DS-437 does not affect the tumor associated macrophage's phenotype, suggesting that PRMT5 inhibition during anti-erbB2 mAb therapy would not be dependent on the macrophage activity." (PMID 30800128, 2019). "Recent studies have shown that ERBB2 (HER2) gene amplification and overexpression may also be actionable in other tumor types." (PMID 31019892, 2019).
tumor (continued). "As expected, expression of the oestrogen (ESR1)/progesterone (PGR) and HER2 (ERBB2) genes were highest in the luminal and HER2-enriched subtypes respectively, and as shown by others, expression of PGR was lower in luminal B tumours relative to luminal A (“PGR”, P < 0.001)." (PMID 30819233, 2019). "No alteration at the ERBB2 gene was found; however, using immunoblotting and IHC it was possible to classify this tumor as HER2‐positive." (PMID 30499260, 2019). "In addition, tumor and normal samples tended to occupy different regions in the ORMDL3-by-ERBB2 graphs." (PMID 30621577, 2019). "Tumour-derived chromosomal copy number changes (1p, 4q loss and 13q gain) and copy number changes of driver alterations including ERBB2 and CDK6 were detected in cfDNA of colorectal and breast cancer patients with good concordance rates when tumour tissue was available for analysis." (PMID 31817150, 2019). "For HER2 and ER expression (positive or negative) in the primary tumor, we checked the pathology report to liken with the expression of ERBB2 and ESR1 in the CTCs at the three different visits." (PMID 31817194, 2019). "ERBB2/HER2 is an oncogene coding for a tyrosine kinase receptor that activates oncogenic pathways related with increase proliferation, angiogenesis and invasiveness, resulting in an highly aggressive neoplasm with poor outcomes that others BC." (PMID 31737566, 2019). "ErbB2 overexpression and KRAS oncogenic mutations also contribute to the selective HK2 induction in tumor tissues, though the mediating machinery is not completely understood." (PMID 31201299, 2019). "We identified seven oncogenes (NRAS, EGFR, RXRA, HRAS, KRAS, AKT1, ERBB2; q<0.10) and seven putative tumor suppressor genes (ARID1A, TXNIP, CTNNB1, PIK3RI, CDKN2A, KLF5, STAG2; q<0.10) significantly regulated between tumor and control, which were formerly reported to be altered in BC." (PMID 30419021, 2018). "An obvious question arises with respect to the clinically HER2+ tumors that do not appear to evidence ERBB2 amplification or HER2 overexpression at the level of the bulk tumor." (PMID 30005627, 2018). "Nevertheless, ErbB2 copy number is not the necessary and the unique factor influencing anti-tumor effect of gefitinib in NSCLC patients." (PMID 29455669, 2018). "One question we asked ourselves was whether we could observe a simple correlation between neratinib protein targets that are down-regulated, e.g. ERBB2 and N-RAS, and the ability of neratinib in combination with valproate to kill the tumor cells." (PMID 29464055, 2018). "Additionally, survivin, MUC-1, CEA, erbB2 and CA19-9 antigens were also detected in a significant number of tumor samples from GBC patients, suggesting that these were suitable antigen targets for immunotherapy approaches." (PMID 29600445, 2018). "We and others found that DUSPs are some of the most robustly regulated downstream targets of EGFR/ErbB2 signaling and indeed both DUSP4 and DUSP6 independently serve key modulatory functions and might be candidate tumor suppressor genes." (PMID 29861842, 2018). "Furthermore, systemic delivery of the nanoparticles carrying the siRNAs to suppress the expression of ER/BCL-2 and ER/ERBB2/EGFR groups of proteins resulted in a notable and sustainable decrease in tumor growth in a 4T1-induced syngeneic mouse model." (PMID 29932151, 2018). "In particular, our results indicate that erbB-2-positive tumor cells derived from MMTV-erbB-2 transgenic mice were sensitive to lapatinib in vitro and the molecular signaling was specifically inhibited in accordance with erbB-2/EGFR-targeting therapeutics." (PMID 28061785, 2017). "Although the sig-pos-AFD enriched genes are largely tumor suppressive, HRAS and ERBB2, which are as well-known canonical oncogenes, are observed to be significantly enriched with sig-pos-AFD missense mutations (P value of 2.37 × 10−09 in HNSC and 9.03 × 10−4 in STAD, respectively)." (PMID 28490743, 2017).
tumor (continued). "No tumors had very high simultaneous EGFR and ERBB2 protein expression (IHC Tumor Cell Score ≥ 2.5), while one Uro tumor had high EGFR and ERBB3 protein expression." (PMID 28388586, 2017). "Three-dimensional tumor spheroid models, as intermediates between monolayer culture and in vivo tumors, comprising of RMS cells were not infiltrated and lysed by WT CIK cells, but by ErbB2-CAR CIK cells which in addition expanded due to tumor recognition." (PMID 29029499, 2017). "Also IBC tumor samples showed amplifications in the following: MYC (8/32; 25%), CCND1 (7/32; 22%), ErbB2 (5/32; 16%), MCL1 (6/32; 19%), and FGFR1 (3/32; 9%)." (PMID 28271309, 2017). "The tumor cell lines (MDA-MB-453, THP-1, RH30, RH41, TE671, A204, Renca-lacZ, Renca-lacZ/erbB-2), peripheral blood mononuclear cells (PBMCs) and the primary aRMS VJ cells were analyzed for the expression of the NKG2D ligands ULBP-2/5/6, and MIC A/B, as well as for the expression of ErbB2 (HER2/neu)." (PMID 29029499, 2017). "In particular, we demonstrate that Blimp1 is highly expressed during p130Cas/ErbB2 dependent invasion in MCF10A.B2 cells and that the modulation of its expression is sufficient to severely impair tumor invasiveness in vitro and lung metastasis formation in vivo." (PMID 28442738, 2017). "This tumor was EGFR (epidermal growth factor receptor), ALK (anaplastic lymphoma kinase), KRAS (V-Ki ras2 Kirsten rat sarcoma viral oncogene homolog), ERBB2 (erb-b2 receptor tyrosine kinase 2), and B-Raf (V-raf murine sarcoma viral oncogene homolog B1) wild-types." (PMID 28915906, 2017). "In particular, African women exhibit molecular profiles in their tumor closer to those of Asian than Caucasian women, and they could dramatically benefit from anti-EGFR and anti-ERBB2 targeted therapies." (PMID 28881604, 2017). "Among the more than 200 HSP90 clients are many proteins required for tumor growth, including primary cancer “drivers” such as BCR-ABL1, wildtype ERBB2 and mutant forms of EGFR, ERBB2, FLT3, JAK2 and KIT, as well as critical downstream effectors of these oncoproteins such as AKT1 and RAF1." (PMID 28032595, 2017). "Alcohol may initially activate EGFR/ErbB2 and/or induce ROS, which stimulate critical signaling components, such as p38 MAPK, Wnt/GSK3β/β-catenin, and TLR4/Nanog, as well as alter tumor microenvironment, resulting in the promotion of CSCs." (PMID 29156633, 2017). "Classifying pT1 UBC tumor samples (all technically valid samples; n=255) by a proprietary algorithm results in the following subtype distribution: 36.9% TNBC, 38.8% Luminal-B, 11.4% Luminal-A and 12.9% ERBB2 positive tumors." (PMID 28978063, 2017). "We also identified three tumors with targetable RTK lesions (PDGFRA, ERBB2, ERBB4) that were exclusive to the recurrent tumor (HGG5, HG8, HGG11), indicating that genomic data from tumor tissue at recurrence may provide better guidance for therapeutic choices." (PMID 29084603, 2017). "We would therefore propose that ErbB2-mediated down-regulation of IFN signaling may also promote metastasis and evasion of anti-tumor immunity." (PMID 28174229, 2017). "This tumor was positive for progesterone receptor (PR), but negative for human epidermal growth factor receptor 2 (HER2, also named as erb-b2 receptor tyrosine kinase 2 (ERBB2))." (PMID 28585435, 2017). "In the absence of external perturbations, the growth of ErbB2-dependent tumours occurs with operational AKT-ErbB3-negative feedback, that is, leading to lower ErbB3 levels, as a result of continued stimulation of AKT." (PMID 27255951, 2016). "Altogether, this argues for the existence of two distinct apoptotic programmes that are executed (i) upon complete ErbB2 blockade in ErbB2-addicted tumours and (ii) during anoikis in the development of normal mammary epithelium without ErbB2 addiction." (PMID 27255951, 2016).
tumor (continued). "Unfortunately, anti-ErbB3 antibodies may not result to be highly efficacious as single agents, because of tumor cells ability to escape from ErbB3 inhibition by activation of EGFR and/or ErbB2." (PMID 26862736, 2016). "Thus, we conclude that both routes to PI3K activation, emanating from ErbB2/Grb2/RAS and ErbB3, must be interrupted to achieve full anti-tumour response." (PMID 27255951, 2016). "We used the nCounter expression assay (NanoString®) to measure the expression of EGFR, erb-B2 receptor tyrosine kinase 2 (ERBB2), ERBB3, ERBB4, and estrogen receptor 1 (ESR1) genes using mRNA extracted from paraffin-embedded tumor tissues from 203 patients diagnosed with TNBC." (PMID 26907936, 2016). "Nuclear GLI1 expression was observed in 26/43 (60%) ErbB2-negative tumor samples and 7/8 (88%) ErbB2-positive tumor samples, and the mean percentage of cells with nuclear GLI1 staining was 37 and 55%, respectively." (PMID 26843616, 2016). "Compensatory mechanisms, such as relief of AKT-ErbB3-negative feedback, are known to desensitize ErbB2-dependent tumours to targeted therapy." (PMID 27255951, 2016). "Our findings provide for the first time a direct signalling evidence linking RAS to evasion of apoptosis in ErbB2-dependent tumours, particularly under the conditions where ErbB2 does not become efficiently inhibited." (PMID 27255951, 2016). "Pertuzumab thus abrogates solely the ligand-stimulated growth without affecting the proliferation of tumour cells driven by ErbB2 overexpression." (PMID 27255951, 2016). "Moreover, the expression of ERBB2 and ERBB3 alone or in combination with resistance markers seem to promote uncontrolled tumor cell growth in overt metastases, leading to a shorter OS." (PMID 27223437, 2016). "Since the cytotoxic effects of the biparatopic agents are by design confined to tumour cells addicted to overexpression of ErbB2, non-tumour tissues with low ErbB2 expression should stay unaffected." (PMID 27255951, 2016). "From these studies and from a screen performed in mice transgenic for activated rat ErbB2 (GJI, MB, ERMB, JH, unpublished data), we obtained MMTV proviral insertion data from a total of 1,132 tumours, of which 35 (3.1%) had insertions that map in the Irs4-locus on the X-chromosome." (PMID 27876799, 2016). "Most CD45−/RFP+/GFP+ cells displayed ErbB2 and F4/80 positivity but were negative for CD11b, suggesting that fusion has occurred between tumor cells and macrophages with acquisition of only a subset of the genes expressed by macrophages." (PMID 27563823, 2016). "SHARPIN expression was significantly elevated in ERBB2 negative compared to ERBB2 positive tumor samples (p < 0.05)." (PMID 26506596, 2015). "In IBC, PDL1 overexpression was associated with estrogen receptor-negative status, basal and ERBB2-enriched aggressive subtypes, and clinico-biological signs of anti-tumor T-cell cytotoxic response." (PMID 25940795, 2015). "Also, integrin β4 interacts with multiple receptor tyrosine kinases, such as EGF-R, ErbB2, and Met and enhances the signaling function of RTKs, in which deregulated joint β4-RTK signaling influences tumor progression." (PMID 25945837, 2015). "To directly test whether the progenitor subset of the luminal epithelium is resistant to ErbB2-initaited tumorigenesis, we injected RCAS-caErbB2 into both Krt6a-tva mice and MMTV-tva mice and compared their tumor latency." (PMID 25635772, 2015). "In this study, one strongly positive ERBB2 tumor existed in the LCNEC group, but no strongly positive ERBB2 tumors were seen in the SCLC group." (PMID 25989941, 2015). "Lapatinib, a clinically approved ERBB2/EGFR inhibitor, counteracts BCAR4-driven tumor cell growth." (PMID 26317614, 2015). "Analysis of the matched primary tumor by aCGH showed that specimen was negative for ERBB2 amplification." (PMID 25970776, 2015).